PI3 (peptidase inhibitor 3)
Diseases named in the same sentence as PI3 in open-access papers (continued):
Sharing a sentence is not in itself a finding about the gene and the disease.
tumor (continued). "In summary, the data highlight the importance of these IRGs in both promoting and preventing tumour progression by indicating a strong correlation between the expression level of genes such as LRP1, PI3, PAEP, FOS, FGF7, and PDGFRA and the degree of tumour immune infiltration in OC." (PMID 39063239, 2024). "Some genes function as tumor suppressor including PLA2G2A, PI3, and NOS2." (PMID 36944972, 2023). "Integrin/FAK, PI3/AKT, and MAPK signalling pathways have been reported to be involved in the activation of the EMT program and induction of several molecular markers responsible for the metastatic potential of tumour cells." (PMID 34204745, 2021). "We found that single gene expressions of IDO1, PI3 and TRIM22 could influence the chemotherapy sensitivity of OC patients in "Analysis based on chemotherapy sensitivity of tumor immune-related genes" section." (PMID 34736480, 2021). "IGF-1 signals intracellularly through the PI3 and MAPK pathways after binding to IGF-1R on the cell surface, and IGF-1 thereby increases the enzymatic activity of MMP-2 and MMP-9 and enhances the proliferation and migration of tumor cells." (PMID 32972437, 2020). "p-FAK may combine with the downstream proteins to activate the PI3/AKT signaling pathway, thereby blocking tumor cell metastasis." (PMID 32952571, 2020). "Our results suggest that the lack of PI3’-lipid signaling in KRASG12D-driven lung tumors is not only limiting in tumor growth, but in propensity for AT2 pneumocyte de-differentiation." (PMID 31452510, 2019). "In addition, the activation of the PI-3 and MAP kinase pathways also induces the expression of thrombospondin-1 and EMT-related genes to promote tumor invasion." (PMID 26859575, 2016). "Consequently, we show that IRF4 controls the expression of tumour suppressor genes known to be silenced by these epigenetic modifications, for instance cyclin-dependent kinase inhibitors CDKN1A and CDKN1B, the PI3-AKT pathway regulator PTEN, and primary cilium components." (PMID 38880659, 2024). "In particular, Plasmodium infection can significantly decrease MMP-9 expression by regulating IGF-1, which might signal intracellularly through the PI3 and MAPK pathways after binding to IGF-1R on the cell surface and thereby increase the expression of MMPs in tumor-bearing mice." (PMID 32972437, 2020). "Thus, recent interesting findings that L1CAM, through PI3 and ERK, can promote cell surface sialyation and fucosylation in CHO cells and stem cells, despite the rapidly emerging relevance of the glycocalyx in tumor biology." (PMID 31455004, 2019). "Such cooperation between blockade of PI3-Akt-mTOR signaling and tubulin cytoskeleton contributes to its anti-proliferative activity observed in vitro against a panel of tumor cells including MDR tumor cells and in vivo antitumor activity in mice bearing human tumor xenografts." (PMID 19293927, 2009).
infection (18 papers, 2011 to 2025). The state of being infected such as from the introduction of a foreign agent such as serum, vaccine, antigenic substance or organism. "Pi3-akt signaling has been implicated in infection of several viruses including that of CHIKV." (PMID 29744032, 2018). "Results from the microarray validated by Q-RT-PCR, and in selected cases at the protein level, indicate a down-regulation of genes such as C1S, LCN2 and PI3 after infection with N. meningitidis relative to N. lactamica." (PMID 22028815, 2011). "Whether and how early transient PI3 downregulation might contribute to protection against infection remains to be determined." (PMID 39667271, 2024). "Indeed, a yet unidentified virion protein(s) do activate the MEK/ERK signalling pathway or do activate the PI3/Akt pathway with integrin beta upon virus entry and also during the early stages of infection." (PMID 38338659, 2024). "Therefore, the objective of this study was to evaluate serological evidence for the presence of infections caused by BoHV-1, BVD, PI3, Neospora caninum, and Leptospira spp." (PMID 35880197, 2022). "This absence of PI-3 excretion remained in the vaccinated group throughout the entire infection phase, further supporting the protective efficacy of the vaccine as shedding of PI-3 was prevented in vaccinated animals." (PMID 41150388, 2025).
bacterial infection (4 papers, 2018 to 2025). "Coupled with the increase in S100A7, IL36G, and PI3, which are associated with bacterial response, these data indicate a compromised epidermal barrier and bacterial infection in high bleeders." (PMID 41156831, 2025). "PI3 is predominantly secreted by neutrophils activated during bacterial infection, responsible for producing two distinct classes of protease inhibitors that participate in immune system modulation and the initiation of antimicrobial defense mechanisms." (PMID 41050698, 2025). "Interestingly, the mRNA encoding peptidase inhibitor 3 (PI3), which plays a role in anti-bacterial and anti-fungal activity, was up-regulated in the nasal epithelium, implying that this gene may help to prevent secondary bacterial infection." (PMID 30487780, 2018).
adenocarcinoma (2 papers, 2014 to 2019). A common cancer characterized by the presence of malignant glandular cells. "Cooperating alterations that activate PI3’-lipid signaling promote progression of BRAFV600E-driven benign tumors to malignant adenocarcinoma." (PMID 31452510, 2019). "A number of adenocarcinoma-specific gene alterations are known, including EGFR, KRAS and BRAF, and these affect the gene products of the MAP kinase and PI3/AKT signaling pathways." (PMID 25364428, 2014).
bladder (2 papers, 2016 to 2019). "Furthermore, niacin treatment promotes activation of the PI3/Akt cascade in human epithelial carcinoma cells." (PMID 26517672, 2016).
colon (2 papers, 2015 to 2024). "EGFR signaling is coupled directly or via adaptor proteins to MAPK signaling, PI3/AKT pathway, which plays a crucial role in DMH/AOM-induced colon carcinogenesis, JAK/STAT (Janus kinase/signal transducer and activator of transcription) pathways." (PMID 26504896, 2015).
respiratory disease (2 papers, 2011 to 2024). "For domestic sheep with signs of respiratory disease (n = 11), there was evidence for antibodies to PI-3 (n = 9) and BRSV (n = 5), but not BVDV-1, BVDV-2, or IBR." (PMID 22195293, 2011).
blood cancers (1 paper, 2025). "While studies hint at AMPK and PI3/Akt signaling pathways controlling mitochondrial morphology and functions in solid tumors, their precise roles in blood cancers are still uncertain." (PMID 41146909, 2025).
heart disease (1 paper, 2021). "Other Secondary prevention drugs for heart disease, such as statins, by activating the PI3/Akt pathway, inducing the differentiation of EPCs, increasing their numbers, and reducing myocardial damage in DM patients." (PMID 33731005, 2021).
inflammation (1 paper, 2020). Aberrant reaction of the microcirculation characterized by movement of fluid and leukocytes from the blood into extravascular tissues. "Inhibition of PI3 decreased bronchoalveolar lavage eosinophils in a murine pulmonary inflammation model." (PMID 32932930, 2020).
PI3 also shares sentences with these, for which no sentence is quoted: infectious disease (4 papers); COVID-19 (3); arrhythmogenic right ventricular cardiomyopathy (2); Hepatic fibrosis (2); pulmonary artery hypertension (2); Sepsis (2); allergic asthma (1); benign tumors (1); brain tumors (1); breast (1); cerebral malaria (1); chronic myeloid leukemia (1); chronic obstructive pulmonary disease (1); Cirrhosis (1); co-infection (1); contact dermatitis (1); Crohn disease (1); cutaneous melanoma (1); cutaneous squamous cell carcinoma (1); dilated cardiomyopathy (1); endometriosis (1); follicular adenomas (1); hepatitis B (1); HIV-1 infection (1); Hypertension (1); inflammatory bowel disease (1); inflammatory skin disease (1); insulinoma (1); ischemic stroke (1); liver cancer (1).
A further 18 diseases each share a sentence with PI3 in 1 paper.